CASP8 (caspase 8)
Diseases named in the same sentence as CASP8 in open-access papers (continued):
Sharing a sentence is not in itself a finding about the gene and the disease.
breast carcinoma (continued). "Evidence has also been found that claudin-1 regulates apoptosis in human breast cancer cells through deactivation of pro-caspase-8." (PMID 33784242, 2021). "Cleaved caspase-8, the activated form of caspase-8, significantly increased in 50 μM embelin treatment of three breast cancer cell lines and increased only in 25 μM embelin-treated MDA-MB-231." (PMID 34282169, 2021). "Beta-sitosterol can promote the apoptosis of breast cancer cells by activating the Fas signaling pathway and caspase-8 activity and is expected to be an orphan nutrition drug against cancer." (PMID 33062007, 2020). "CASP8 has multiple functions in different contexts, with a possible essential role in breast cancer cell lines." (PMID 31980032, 2020). "Another mechanism elaborated on the initiation of apoptosis for breast cancer cells BT-20 is the formation of RIP1-FADD-caspase-8 complex via CIAP2/RIP1 pathway." (PMID 32028721, 2020). "A reduced mRNA level of CASP8 was recently reported in breast tumors collected from the subjects diagnosed with breast cancer." (PMID 32612536, 2020). "This included 7 breast cancer-related genes: caspase 8 (CASP8), cadherin 1 type 1 (CDH1), estrogen receptor 1 (ESR1), ETS variant 6 (ETV6), forkhead box A1 (FOXA1), GATA-binding protein 3 (GATA3) and neurotrophic tyrosine kinase receptor type 3 (NTRK3)." (PMID 31182966, 2019). "The caspase 8 variants CASP8 -652 6N InsDel and Asp302His have previously been identified to promote survival of T-lymphocytes and to indicate reduced breast cancer susceptibility." (PMID 31467295, 2019). "All factors considered, our data suggests that CASP8 plays an apoptotic role in breast cancer, suppressing tumor malignancy." (PMID 31757997, 2019). "We report on a prognostically favorable influence of the CASP8 -652Del and the 302HisHis in early breast cancer and demonstrate that the 302HisHis genotype correlates with low TIL concentration." (PMID 31467295, 2019). "Sharifi S revealed that doxorubicin promoted mitochondrial-dependent apoptosis through up-regulating the expression levels of Bax, caspase-8 and caspase-9 in breast cancer cells." (PMID 30651744, 2019). "Caspases have tumor suppressor functions, and in breast cancer cells, downregulation of CASP8 has been reported." (PMID 30980596, 2019). "Especially for cell-survival effects in breast cancer cells, FAK inhibition by a dominant negative mutant drives the apoptotic process via Fas-associated death-domain protein and caspase-8." (PMID 31480645, 2019). "We also evaluate the effect of the obtained fractions and Sarcophine on expression of caspase-3 and caspase-8 in MDA-MB-231 breast cancer cells." (PMID 29881421, 2018). "Upon caspase 8 activation, lipoatrophy of the mammary gland results in stromal fibrosis and acceleration of mammary tumor development with an increase in tumor multiplicity." (PMID 29487713, 2018). "The death receptor-related proteins Fas/FasL, TNFR1, and DR5 were detected by Western blot, it showed that different breast cancer cells activated the death receptor-mediated extrinsic caspase-8 pathway through different receptors." (PMID 28184196, 2017). "We demonstrated that the activity of caspase 8 was increased in a dose-dependent manner in both breast cancer cell lines however the level of caspase 8 activity was remained unchanged in normal breast cells." (PMID 29096636, 2017). "Caspase-8 activity is pre-requisite for Par-4 cleavage in TNF-α induced cell death is reported in breast cancers." (PMID 29278364, 2017). "Given the remarkable role of caspase cascade as an executors of apoptosis, the possible involvement of caspase 3 and caspase 8 in sodium butyrate-induced apoptosis in breast cancer and normal cells were evaluated." (PMID 29096636, 2017). "In summary, after correction for multiple testing, one of the twelve CASP8 SNPs tested in our study remained nominally statistically significantly associated with invasive breast cancer, specifically, HER2-positive breast cancer." (PMID 26758508, 2016).
breast carcinoma (continued). "The minor allele of two caspase 8 polymorphisms, namely CASP8 -652 6N InsDel (rs3834129) and CASP8 Asp302His (rs1045485), were repeatedly associated with reduced breast cancer susceptibility." (PMID 27507139, 2016). "In the present study, we investigated clinical relevance of two selected caspase 8 polymorphisms, namely CASP8 -652 6N InsDel and Asp302His, for patients with primary breast cancer." (PMID 27507139, 2016). "The CASP8 SVA-E retrotransposon described here is associated with increased risk of BCC and breast cancer, but decreased risk of prostate cancer." (PMID 26740556, 2016). "The mechanistic and functional consequences of CASP8 SNPs in breast cancer development and their relevance in women of other racial/ethnic groups remain to be investigated." (PMID 26758508, 2016). "By contrast, caspase 8, a protein that self-cleaves as a result of the activation of the extrinsic pathway, maintained expression when breast cancer cells were exposed to arantho EO." (PMID 27491777, 2016). "An increase of caspase-7 and caspase-8 activity was noted in human breast carcinoma cells when treated with Linola flax straw extract." (PMID 27630565, 2016). "The CHEK2, TGFβ1, CASP8 and ATM genes belong to the ‘low to moderate-risk’ breast cancer susceptibility genes." (PMID 26124080, 2015). "We also came across literature evidence highlighting the critical role of Casp8 for affecting breast cancer directly." (PMID 25707537, 2015). "This study deals with the role of other caspases, i.e. initiator caspase-8 and -9 as well as executioner caspase-3 and -7 in taxane-induced cell death in breast cancer cells." (PMID 25685064, 2015). "In our study, treatment with CDDO-Me, even at a low concentration, consistently reduced c-FLIPL protein levels in breast cancer cells while very effectively promoting caspase processing, in particular that of caspase-8." (PMID 26053096, 2015). "SVT inhibited the proliferation, altered the cell cycle and enhanced the induction of apoptosis of breast cancer cells by increasing the activities of caspase-3, caspase-8 and caspase-9." (PMID 26061816, 2015). "In our previous study, we described the activation of caspase-8, -9 and -3 in sensitive and resistant breast cancer cells after apoptosis induction by paclitaxel, the novel taxane SB-T-1216 as well as certain novel fluorinated taxanes." (PMID 25685064, 2015). "Our cell-based FRET assay allows for an unprecedented detection of both caspase 3 and caspase 8 activity in a microplate format using a human breast cancer cell line." (PMID 25188024, 2014). "Hypermethylation of the caspase-8 gene has been detected in childhood neuroblastomas, lung tumors and cell lines, pedriatric tumors and cell lines, breast cancer cells, and several others." (PMID 24618889, 2014). "It was found that caspase-3/7, caspase-9 and caspase-8 were all activated significantly when the breast cancer cell lines MCF-7 and MDA-MB-231 were treated with SAMC." (PMID 25070343, 2014). "We also have demonstrated that c-FLIPL interacts with DR5, FADD, and caspase-8 forming an Apoptotic Inhibitory Complex (AIC) in MCF-7 breast cancer cells." (PMID 25379355, 2013). "Previously, it was demonstrated that dandelion (Taraxacumofficinale) aqueous extracts, used in traditional medicine for treatment of leukemia and breast cancer, exhibited activation of caspase-8 in human leukemia cells." (PMID 24039967, 2013). "Immunoblot analysis also revealed that FAE treatment induced a dose-dependent cleavage of Caspase 7, Caspase 8 and Caspase 9 in breast cancer cells, MCF-7 and T47D, suggesting the activation of mitochondria mediated pathway in apoptosis." (PMID 22792212, 2012). "Other loci previously found to be associated with BRCA1 breast cancer risk include the 19p13 and 6q25.1 loci, TOX3 and CASP8." (PMID 22348646, 2012).
breast carcinoma (continued). "We recently discovered that c-FLIPL interacts with DR5, FADD, and caspase-8 forming an apoptotic inhibitory complex (AIC) in MCF-7 breast cancer cells." (PMID 22348197, 2011). "The ability to de-repress either caspase-8 or -10 via FLIPi helps to explain the broad range of breast cancer cell types affected." (PMID 21914219, 2011). "Recent results demonstrated that TRAIL-triggered apoptosis in breast cancer cells is blocked at the level of apical activation of caspase-8, and that SAHA enhances the TRAIL-induced processing and activation of procaspase-8." (PMID 22348197, 2011). "Demethylation agent 5-aza-2'-deoxycytidine (5-aza-dc) selectively inhibits DNA methyltransferases, DNMT3a and DNMT3b, and restored CASP8 and maspin gene expression in breast cancer cells." (PMID 20132554, 2010). "Results also confirmed that CASP8 gene and protein can be restored by demethylation in selected breast cancer cells." (PMID 20132554, 2010). "Bisulfite sequence analysis demonstrated the position of the methylated CpG sites of CASP8 in different breast cancer cells." (PMID 20132554, 2010). "Up to now, except for interferon-γ and azacytidine, the cytotoxic drugs, 5-Fu and methotrexate, have been shown to upregulate CASP8 and induce cell apoptosis in neuroblastoma, medulloblastoma, Ewing sarcoma, glioblastoma, leukemia, and breast cancer cells." (PMID 20132554, 2010). "Bisulfite sequencing confirmed the position (nt -642 to nt -532, located in CASP8 core promoter region) of demethylation of CASP promoter by 5-Fu in these breast cancer cells." (PMID 20132554, 2010). "We confirmed that CpG sites methylation in the promoter region of CASP8 is the mechanistic basis for transcriptional downregulation or silencing of CASP8 in breast cancer cells." (PMID 20132554, 2010). "Recent studies have shown that the anticancer drug, 5-fluorouracil (5-Fu), can upregulate CASP8 protein and induce cell apoptosis in leukemia and breast cancer cells." (PMID 20132554, 2010). "In this study we have also examined maspin and CASP8 mRNA levels in 30 breast cancer tissues and 10 non-breast cancer tissues." (PMID 20132554, 2010). "In MCF-7 human breast cancer cells, caspase 8 activation appears to be due to the activation of caspase 9 within the apoptosome, as caspase 8 processing is inhibited by overexpression of the anti-apoptotic protein Bcl2." (PMID 19609365, 2009). "The possibility exists that phospho-ablated Id2 interacts with the death domain cascade, as caspase 8 has been shown to activate caspase 3 in MDA-MB231 breast cancer cells treated with etoposide." (PMID 19609365, 2009). "There is evidence from the Breast Cancer Association Consortium that CASP8 (caspase 8) and TGFB1 (TGF-β1) variants impart risk, albeit low penetrance, for breast cancer." (PMID 17940599, 2007). "Knockdown of E4F1 resulted in an increase in CASP8 levels while IRF2 knockdown results in reduction of CASP8 RNA levels in melanoma, breast cancer, and melanocytes, consistent with respective roles for E4F1 and IRF2 as a potential repressor and activator in cells of melanocytic lineage." (PMID 41542517, 2026). "Notably, elevated levels of CASP8, latency-associated peptide of transforming growth factor beta-1 (LAP TGF-β1), HGF, and ARG1 were observed among breast cancer patients diagnosed within 5 years of follow-up." (PMID 40665092, 2025). "Interestingly, both breast cancer cell lines incubated with a mix consisting of rGO and MG-132 showed increased percentages of active caspase-8 and active caspase-9 compared to the examined cells incubated with only rGO or only with MG-132." (PMID 38791473, 2024). "For example, we identified 3′aQTLs in the caspase 8 (CASP8) gene that strongly colocalized with GWAS risk loci across multiple cancers, including skin cancer (PP4 = 0.961), breast cancer (PP4 = 0.973), and basal cell carcinoma (PP4 = 0.915), but not with eQTLs nor sQTLs." (PMID 38409266, 2024).
breast carcinoma (continued). "Another dammaranes, cabralealactone 3-acetate and its methyl ether, which contain a tetrahydrofurane substituent replacing the hydrocarbon chain at C17, increased the level of death receptors DR4 and DR5, leading to activation of caspase-8 in breast cancer cell line MCF7." (PMID 39274939, 2024). "Also, Fridamycin-H decreased Caspase-8 in breast cancer cells in vitro, suggesting it is a promising candidate for future in vivo studies in breast cancer models." (PMID 39272080, 2024). "Interestingly, both breast cancer cell lines incubated with a mix consisting of rGO and MG-132 showed increased percentages of active caspase-8 and active caspase-9 compared to examined cells incubated with rGO or with MG-132." (PMID 38791473, 2024). "The present study suggests that coffee extract might affect apoptosis in breast cancer cells by increasing Caspase-8 levels, proliferation by reducing β-catenin expression, and oxidative stress by decreasing malondialdehyde (MDA) levels." (PMID 39272080, 2024). "Thus, CL-nanoemulsion induces apoptosis in breast cancer cells by inducing caspase-8 and -9 activity and suppressing VEGFR-2." (PMID 37570781, 2023). "Autophagy has been reported for lectins from Polygonatum odoratum on MCF-7 breast cancer cells, and its mechanism of action on L929 murine fibrosarcoma cells involves the activation of caspase 8, 9, and 3, and increased levels of expressed FasL and FADD death receptors." (PMID 37259433, 2023). "Additionally, in MDA-MB-231 breast cancer cells, it increased caspase-8 and -9 activity, decreased MMP and induced cytochrome c release." (PMID 36675194, 2023). "Similarly, in the present study, 3HDT induced more γH2AX and 8-OHdG levels of DNA damage as well as apoptosis (annexin V, caspase 3, caspase 8, and caspase 9) in breast cancer cells than in normal cells, which was reverted by NAC pretreatment." (PMID 36982818, 2023). "A previous study found that caspase-3 expression, but not caspase-8, in breast cancer tissue was associated with worse survival in early-stage breast cancer patients with hormone receptor positive, and non-basal like subtype BC." (PMID 36945037, 2023). "Moreover, a cross-talk between this pathway and caspase-8 was also observed for Exe in sensitive and resistant breast cancer cells when autophagy, PI3K, and AR were targeted." (PMID 37173983, 2023). "For the non-steroidal AI Ana, it was also reported that the induction of apoptosis in breast cancer cells occurred via the mitochondrial pathway, but also by the up-regulation of caspase-8 by an unknown mechanism." (PMID 36677847, 2023). "Also, the anticancer impact of CL-nanoemulsion is due to the induction of apoptosis in MCF-7 breast cancer cells by increasing caspase-8 and -9 activity and decreasing VEGFR-2 compared with CL-emulsion." (PMID 37570781, 2023). "A similar behavior has also been reported for Exe in this cell line, although Oxy has an advantage, as in addition to activating the mitochondrial apoptotic pathway, it also activates caspase-8, which may promote a more efficient breast cancer cell death." (PMID 36677847, 2023). "Similarly, it was determined that there was a decrease in the levels of CASP8 in patients with breast cancer." (PMID 37529254, 2022). "A recent study on the role of NPD-L1 and TNFα in breast cancer showed that under hypoxia, PD-L1 can migrate to the nucleus and activate GSDMC, which is then cleaved by the TNFα activated-caspase-8, triggering pyroptosis and promoting the death of breast cancer cells." (PMID 35359956, 2022). "Moreover, we detected a clear increase of caspase-3 and -7 activity in both the breast cancer cells treated with compounds 1 and 6, which it is known are cleaved and activated by the initiator caspase-8." (PMID 35631334, 2022).
breast carcinoma (continued). "Here, we also found that a high CASP8 expression was most enriched in the RIG_I_LIKE pathway, which might have anti-cancer functions in breast cancer, prostate cancer, and ovarian cancer cell lines, and colorectal cancer human cancer tissues." (PMID 35928267, 2022). "DHA induces apoptosis in MCF-7 breast cancer cells in vitro, probably via caspase-8 activation." (PMID 35745191, 2022). "Additionally, IRF1 has been shown to have tumor suppressor functions in breast cancer through its inhibition of NF-kB36 and CASP8 activation and induction of apoptosis." (PMID 34234117, 2021). "Gynecological tumors such as ovarian and breast cancers are associated with increased aggressiveness and invasiveness, when caspase-8 is downregulated or is absent." (PMID 33026575, 2021). "GSDMC was then cleaved by caspase-8 in breast cancer cells treated with TNF-α." (PMID 33634141, 2021). "While this is a novel finding, we are unsure that this mechanism is relevant in vivo, as our previous work in breast cancer showed that ONC201 inhibited the growth of xenografted tumors only if the effects of the compound in vitro involved caspase-8 cleavage and TRAIL-dependent apoptosis." (PMID 33144917, 2020). "Notably, AdoMet efficiently activated caspase 8 by FAS-mediated signaling in hormone-dependent breast cancer cells while it induced apoptosis in HNSCC via the intrinsic mitochondrial pathway." (PMID 33202711, 2020). "Moreover, we investigated prognostic significance of combined -652 InsDel and Asp302His genotypes in breast cancer patient and referred to the different CASP8 diplotypes." (PMID 31467295, 2019). "High caspase-3 expression, but not caspase-8, is significantly associated with adverse breast cancer-specific survival (P = 0.008 and P = 0.056, respectively)." (PMID 27798717, 2017). "Caspase 8 (CASP8) mutations were associated with higher T and NK cell estimates and lower Treg/CD8 ratios in head/neck cancer, and a specific Q156 nonsense mutation was associated with higher NK cells in breast cancer." (PMID 28749946, 2017). "Because DR4 and DR5 trigger the extrinsic apoptosis pathway on binding to its ligand TRAIL by cleavage and activation of the effectors caspase-8 and caspase-3, we investigated whether miR-17-5p/20a increase cell apoptosis in breast cancer." (PMID 29179464, 2017). "Similarly, a study has shown a reduction of EGFR activation in EPA- or DHA-induced apoptosis in breast cancer (MDA-MB-231 and MCF-7) cells, associated to a reduction of Bcl2 and caspase-8 expression." (PMID 28869531, 2017). "Neither caspase-3 nor caspase-8 protein expression was significantly associated with breast cancer-specific survival in any of the groups (data not shown)." (PMID 27798717, 2017). "Patients with high caspase-3/high calpain-1 expression, high caspase-3/high calpain-2 expression, high caspase-3/low calpastatin expression, or high caspase-8/low calpain-1 expression had significantly worse breast cancer-specific survival (P = 0.005, 0.049, 0.02, and 0.02 respectively)." (PMID 27798717, 2017). "Furthermore, in this breast cancer cell line DoHuRu/DOTAP seemed able to promote full length pro-caspase-8 cleavage, as evidenced by the formation of the active p10 and p18 fragments." (PMID 28349991, 2017). "As our key finding, we described both caspase 8 variants as a negative prognostic factor for breast cancer." (PMID 27507139, 2016). "Moreover, to investigate prognostic significance of combined CASP8 -652 6N InsDel and CASP8 Asp302His genotypes in breast cancer patients, we used CASP8 diplotypes." (PMID 27507139, 2016). "The second new report involves the use of population whole-genome sequencing to identify a full-length SVAE insertion (2792 bp in length) into intron 8 of the caspase 8 (CASP8) gene associated with increased susceptibility to cutaneous basal cell carcinoma (BCC) and breast cancer." (PMID 27158268, 2016).